BRAF (B-Raf proto-oncogene, serine/threonine kinase)
Diseases named in the same sentence as BRAF in open-access papers (continued):
Sharing a sentence is not in itself a finding about the gene and the disease.
tumor (continued). "Among them, high iodine intake is a high-risk factor for BRAF gene mutations in PTC patients; RET gene testing can be performed for MTC patients, and RET mutations are closely related to tumor invasiveness and poor prognosis." (PMID 41323380, 2025). "In recent decades, genomic studies revealed the importance of the oncogenic driver mutations in BRAF, NRAS, NF1, and KIT genes in tumor development." (PMID 40075679, 2025). "The increased sensitivity of PDOs derived from left-sided RAS/BRAF-WT tumors to panitumumab confirms our previous observations, reinforcing that tumor characteristics influencing targeted drug response are preserved in PDOs." (PMID 40982295, 2025). "PI3K pathway mutations, observed in both DTC and ATC, are less frequent than BRAF and TERT mutations but are consistently linked to survival outcomes, underscoring their role in tumor progression." (PMID 40149275, 2025). "Genes enriched in GNAQ-UM and BRAF-CM were identified by those with a Log2FC > 1 and Adj p-value < 0.0001 between the two tumor types." (PMID 40950146, 2025). "Agents such as vemurafenib and encorafenib have demonstrated effectiveness in selectively inhibiting mutant BRAF, leading to tumor shrinkage in some cases of CRC." (PMID 40429703, 2025). "Patients harboring NTRK fusion exhibit more aggressive tumor behavior, with a higher risk of distant metastases and RAI refractoriness compared to those with RAS or BRAF mutations." (PMID 40507281, 2025). "Collectively, these data suggest a complex and distinct immune phenotype between KIAA1549‐BRAF fusion and BRAF V600E, suggesting the involvement of potentially different immune pathways in these tumor subtypes." (PMID 40588233, 2025). "Preclinical and early clinical studies demonstrate that dual inhibition—such as combining MEK and PI3K inhibitors—can induce synergistic apoptosis and tumor regression, particularly in tumors harboring KRAS, BRAF, or PIK3CA mutations." (PMID 40943615, 2025). "The anti-proliferative activity of tovorafenib and TAK-632 was evaluated by CTG cell viability assay at 72 hours after treatment in the NF1-LOF tumor cell lines and the BRAF V600E tumor cell line, A375." (PMID 40111124, 2025). "This study also highlights the potential role of BRAF/MEK inhibitors in BC oncogenesis and underscores the need for alternative biomarkers, such as tumor mutation burden (TMB) and circulating tumor DNA (ctDNA), to guide treatment selection in BC better." (PMID 40002790, 2025). "High TIMP1 histoscore in both tumor epithelial and stromal cells strongly associated with proximal tumor location, MMR deficient status, and BRAF mutation (all p < 0.001)." (PMID 39789100, 2025). "BRAF immunohistochemistry (IHC) serves as a surrogate for BRAF p.V600E but shows variable performance across tumor types and institutions." (PMID 40689945, 2025). "The mean maximum tumor diameter was 1.08 cm (SD 0.73), and the mean BRAF V600E abundance was 21% (SD 12)." (PMID 41228353, 2025). "All 20 tumor tissues displayed the known mutations with mean MAF of 34% in H3F3A K27M (ranging from 8 to 80%) and 25% in BRAF V600E (ranging from 4 to 40%), respectively." (PMID 39751690, 2025). "Tumor heterogeneity and adaptive resistance—such as bypass signaling in BRAF(+) CRC or secondary fusions—underscore the complexity of interpreting agnostic biomarkers into durable treatment tactics." (PMID 40868288, 2025). "Tumor- and CRC-specific mutations were mostly synonymous or low-impact variants in genes including AKT1 (YCLO-2), BRAF (YCLO-2), FGFR3 (YCLO-7), and PIK3R1 (YCLO-7)." (PMID 40462147, 2025). "Altogether these results showed that BRAF/MEKi resistance is sustained by an immunosuppressive TME associated to increased expression of miR-99b, miR-125a, and let-7e at the tumor site." (PMID 41550951, 2025).
tumor (continued). "Also, in the context of BRAF-mutant CRC, the activation of the MAPK signaling pathway, induced by the BRAF-mutation, may contribute to increased expression of immune evasion-related proteins, such as PD-L1, thereby enhancing the tumor’s vulnerability to immunotherapy." (PMID 40149341, 2025). "Together, oncogenic BRAF aberrations result in constitutive activation of BRAF protein kinase activity, leading to downstream signaling that drives tumor growth and proliferation." (PMID 40007996, 2025). "The tumor characteristics of patients were predominantly consisting of BRAF wildtype (100%), microsatellite stable (MSS) (90%), and high TILs score (80%) while RAS mutant and wildtype showed similar proportion (52% and 48%, respectively)." (PMID 40140197, 2025). "This study also aimed to correlate BRAF p.V600E mutational status with characteristics including PTC subtype, T and N category, tumor size, nodal disease burden, loco-regional recurrence, and distant metastasis." (PMID 40237893, 2025). "This paradoxical ERK1/2 activation limits efficacy in BRAF wild type tumours but also drives adventitious growth of low-grade tumours in tissue that lacks BRAFV600E/K18." (PMID 41249187, 2025). "Heterogeneity in tumor biology (e.g., RAS/BRAF mutations), patient comorbidities, and institutional preferences often leads to inconsistent treatment strategies." (PMID 40805233, 2025). "In conclusion, BRAF mutations, particularly the V600E mutation, are crucial in the pathogenesis of PTC, influencing tumor characteristics, treatment response, and providing avenues for targeted therapies." (PMID 39744583, 2025). "Targeted therapies that combine BRAF and MEK inhibitors have shown promising tumor-agnostic clinical activity against BRAF V600E-positive solid tumors." (PMID 40844731, 2025). "Reactivation of this pathway allows tumor cells to evade BRAF inhibition, thus promoting proliferation." (PMID 40872623, 2025). "Patients with BRAF-V600Emt tumours received fewer treatment lines, less intensive treatments, and the intent in first line was palliative more often compared with RASmt and RAS&BRAFwt." (PMID 40437037, 2025). "Baseline ctDNA BRAF V600E correlated significantly with tumor burden (p < 0.05), and concentrations decreased significantly at the first month of therapy and at best response (p < 0.05)." (PMID 39859576, 2025). "The genomic landscape of Spitz neoplasms includes fusions in genes such as ALK, ROS1, MET, RET, or BRAF and mutations in HRAS genes, which influence both the tumor’s biological behavior and morphological features." (PMID 40870546, 2025). "Among these genetic alterations, BRAF V600E is one of the most common mutations in PTC, carried by approximately 45–60% of patients and closely associated with tumor initiation, progression, and adverse prognosis." (PMID 41228353, 2025). "The patient’s case was discussed at the multidisciplinary tumor board, and it was decided to initiate dual BRAF/MEK inhibitor therapy (dabrafenib/trametinib)." (PMID 39976897, 2025). "In a study performed in 2017 that dealt with 48 mutant BRAF profile patients, 53% of patients receiving Cetuximab had early tumor shrinkage, compared to 33% receiving Bevacizumab." (PMID 40943615, 2025). "The mutational profile of CRC tumors, including KRAS, NRAS, BRAF, PIK3CA, and AKT1 gene mutation and MSI status significantly influences the characteristics of the tumor microenvironment (TME) and directly impacts patient prognosis." (PMID 40724985, 2025). "The tumor harbored a pathogenic ATRX pI1049fs mutation, BRAF:KIAA1549 gene fusion, monosomy of chromosome 1p and distal 19q, and trisomy of chromosome 1q." (PMID 40377441, 2025). "This mutation is also observed in melanomas, and BRAF and MEK inhibitors such as vemurafenib, dabrafenib, and trametinib have revolutionized the treatment of these neoplasms, with promising results also for PCPs." (PMID 40433410, 2025).
tumor (continued). "Since then, additional agents have secured tumor-agnostic FDA indications, including targeted therapies for NTRK gene fusions, BRAF V600E mutations, RET fusions, as well as treatments based on high tumor mutational burden (TMB-H) or HER2 overexpression." (PMID 41228293, 2025). "After discussion of the patient’s case at multidisciplinary tumor board, the decision was made to start the patient on dual BRAF/MEK inhibitor therapy (dabrafenib/trametinib)." (PMID 39976897, 2025). "The significant contribution that KRAS, BRAF, and NRAS mutations predominate in serous borderline precursors suggests a stepwise model for tumor development and reinforces the importance of MAPK signaling in the biology of disease." (PMID 41376748, 2025). "Erastin, a ferroptosis inducer first discovered in 2003, was found to exhibit considerable lethality in human tumour cells harbouring mutations in the HRAS, KRA, and BRAF oncogenes." (PMID 40136465, 2025). "First, we analyzed the tumor tissue of 20 patients in our cohort and isolated the genomic DNA (11 H3F3A K27M, 8 BRAF V600E and 1 H3F3A K27M/BRAF V600E double mutation) to validate our ddPCR method." (PMID 39751690, 2025). "Patient 1 received the combination of dabrafenib (RAFi) and trametinib (MEKi), and Patient 2 received trametinib (MEKi), treatment recommendations that were guided by tumor genetic profiling (BRAF p.V600E and HRAS p.G13R, respectively)." (PMID 40634537, 2025). "We demonstrate that ALDH2 downregulation enhances MAPK/ERK activation, promotes tumor growth, and confers resistance to BRAF and MEK inhibitors." (PMID 40558540, 2025). "A 66-year-old man with rectosigmoid junction CRC initially showed RAS/BRAF wild-type status, microsatellite stability (MSS), and a moderate tumor mutational burden (TMB: 7.1 mutations/Mb) on the primary tumor." (PMID 40842629, 2025). "Further large-scale prospective studies are warranted to validate our findings and clarify the prognostic implications of tumor sidedness in BRAF V600E-mutant mCRC." (PMID 40761242, 2025). "BRAF mutations trigger the constitutive activation of the MAPK/ERK signaling pathway, promoting uncontrolled cell proliferation and tumor survival." (PMID 39897423, 2025). "For example, the FDA-approved combination of MEK and BRAF inhibitors effectively halts tumor progression in KRAS/BRAF-mutant patients with NSCLC." (PMID 41050683, 2025). "Quantitative analysis of tumor-specific mutations in ctDNA, such as single nucleotide variants in KRAS, NRAS, PIK3CA, BRAF, and EGFR, demonstrated over 80 % concordance with tumor tissue in patients with colorectal, lung, and breast cancers." (PMID 40144458, 2025). "Consistent with the findings for mucinous differentiation, the expression of all mucins was increased in tumours with proximal colon location, high tumour grade, MMR deficiency, and BRAF mutation." (PMID 39966658, 2025). "Tumor-agnostic approvals have a portfolio of TMB, dMMR, MSI, NTRK fusion, RET fusion, and BRAF mutations; each of which is actionable by giving a specific class of FDA-approved agents." (PMID 40183077, 2025). "Gene effect values approaching –1 suggest that suppression of ITGB1, TIMP3, or BRAF severely compromises tumor cell viability." (PMID 41294900, 2025). "Approximately 5–15% of CRC patients harbor BRAF mutations, more than 90% of which is BRAF V600E mutation, leading to prolonged activation of the MAPK pathway and promoting tumor progression." (PMID 39934467, 2025). "This tumor is often accompanied by BRAF gene variation and exhibits a relatively well-circumscribed growth pattern, with an overall good prognosis." (PMID 40927709, 2025). "Controlling for these variables in future research will provide a more nuanced understanding of the interplay between BRAF V600E AF and tumor behavior." (PMID 40805249, 2025).
tumor (continued). "Although targeted therapies can be an effective strategy for treating cancer, the duration of responses to such therapies, for example, BRAF inhibitors (BRAFi), varies substantially and can be dependent on the origin of the primary tumor." (PMID 40080754, 2025). "These tumours also express tumour‐associated genetic markers (e.g., CD44v6, CDX2, BRAF) and immune markers (e.g., CD68, CD163), alongside characteristics like CpG island methylator phenotype and KRAS mutations." (PMID 40444502, 2025). "Class I mutations exclusively co-occurred with BRAF or NRAS mutations, while Class II and III mutations often acted as sole tumour drivers." (PMID 40107205, 2025). "BRAF mutations, and more specifically the common BRAF V600 mutation, cause continuous activation of the MAPK/ERK pathway, which leads to continuous activation of tumor growth pathways." (PMID 39857950, 2025). "Recent studies also suggest that BRAF/MEK inhibition can enhance tumor immunogenicity by increasing the presentation of tumor antigens, providing further synergy with ICIs." (PMID 39897423, 2025). "Resistance and Regulatory Challenges: How does tumor heterogeneity impact treatment response (e.g., differential progression-free survival in BRAF-mutant vs. wild-type patients)?" (PMID 40977706, 2025). "Although this review is focused on the detection of BRAF V600E in ctDNA through liquid biopsy, it is essential that evidence from tumor tissue-based studies is also considered." (PMID 40977811, 2025). "Beyond the reduction of tumour burden and recurrence, neoadjuvant BRAF/MEK inhibition has the potential to facilitate organ-preserving surgeries, minimise functional and aesthetic impairment, and enhance long-term quality of life." (PMID 41364259, 2025). "Alongside trials exploring BRAF inhibitors alone, BRAF and MEK inhibitors are being explored as combination therapy to reduce the possibility of tumor resistance commonly associated with single-agent BRAF inhibitors." (PMID 40042714, 2025). "In contrast, SUVmax and TLG directly quantify tumor-intrinsic glycolytic activity, aligning with BRAF-driven metabolic reprogramming." (PMID 40969790, 2025). "We performed bulk cytokine analysis on media collected from tumor and immune cells following a short culture and compared the secretion profile between BRAF V600E and KIAA‐1549:BRAF fusion samples." (PMID 40588233, 2025). "Though not significant, there was a trend toward higher concentrations of cytokines secreted by KIAA‐1549:BRAF fusion samples for both tumor and immune cells." (PMID 40588233, 2025). "Patients receiving either therapy showed an increased number of primary tumours with a thickness of more than 2 mm (PD‐1: 22 (64.7%), BRAF + MEK: 19 (56.6%))." (PMID 40331873, 2025). "This phenomenon involves the transcriptional silencing of tumor suppressor genes (including BRCA1/BRCA2, TP53BP1, SMAD4) and the abnormal activation of oncogenes (such as PDGFRA, PIK3CA, and BRAF), thereby facilitating tumor initiation and progression." (PMID 40927709, 2025). "We applied our ddPCR assay as a surrogate marker to monitor our patient's tumor burden and predict the efficacy of anti-BRAF therapy." (PMID 41245504, 2025). "The most common mechanisms of resistance to anti-EGFR therapy are mutations in RAS genes, secondary mutations in BRAF, EGFR or HER2 genes, and also tumor heterogeneity." (PMID 40002260, 2025). "Both tumours showed significant shrinkage and sustained remission for 12 months, demonstrating the potential of BRAF‐targeted therapies for treating multiple BRAF V600E‐positive cancers." (PMID 39950095, 2025).
tumor (continued). "In this same context, a prospective study, including 43 MM patients, BRAF, NRAS and KIT mutations in ctDNA and basal concentration were analyzed using ddPCR and correlated with basal and changes in tumor burden and OS (p < 0.05)." (PMID 39859576, 2025). "High Th1 cell densities were associated with female sex, proximal tumor location, low disease stage, high tumor grade, less frequent lymphovascular invasion, MMR-deficient status, and BRAF mutation in both cohorts." (PMID 40928327, 2025). "To better understand the potential applications of immunotherapy in BRAF-mutant NSCLC, we analyzed the tumor mutation burden and the fraction genome altered between all three BRAF mutation classes using data from cBioPortal." (PMID 41152458, 2025). "In these cases, BRAF alterations function as tumor-agnostic predictive biomarkers, similar to NTRK1, NTRK2, and NTRK3 (NTRK1-3) gene fusions, supporting the rationale for broad molecular profiling and precision targeting strategies in rare GI tumors." (PMID 41153346, 2025). "This study highlights the prognostic significance of HIF-1α, LOX and ITGA5 expression in the tumor microenvironment, particularly in the context of KRAS/NRAS/BRAF mutation status." (PMID 39857068, 2025). "Molecular markers such as RAS (KRAS/NRAS) mutations, BRAF mutations, HER2 amplification, microsatellite instability (MSI) or mismatch repair (MMR) status, and tumor mutational burden (TMB) have become central to therapy selection and prognosis." (PMID 41228293, 2025). "First, an in silico exploration was conducted to identify and characterize the BRAF/MEK/PI3K oncogenic signature in CRC, demonstrating how mutations and differential expression remodel the tumor microenvironment and impact overall patient survival." (PMID 41009348, 2025). "Survival by BRAF status in stage I, III and IV tumours had overlapping CIs, but cohort numbers were smaller for these groups, and all but stage III tumours showed a trend towards worse outcomes in BRAF-mutated tumours." (PMID 40902091, 2025). "This supports a biological link between BRAF V600E mutations and the serrated pathway of carcinogenesis, which is associated with CpG island methylator phenotype (CIMP), right-sided tumor location, and mucinous differentiation." (PMID 41439081, 2025). "Tovorafenib demonstrated anti-tumor activity in relapsed/refractory BRAF-altered OPG across radiological assessment criteria and was generally well tolerated." (PMID 39700439, 2025). "While dabrafenib directly inhibits BRAF activity, HT induced a broader suppression of oncogenic proteins involved in tumor-stroma crosstalk and angiogenesis, including VEGFR-2, WIF-1, ITGB5, and ERBB2/3/4." (PMID 40725203, 2025). "This compensatory activation diminishes the efficacy of BRAF inhibitors, limiting their ability to suppress tumor growth." (PMID 40129883, 2025). "Therapeutic inhibition of mTORC1 by rapamycin and blockade of BRAF/MEK signaling constitute a targeted intervention to suppress tumor progression." (PMID 40955667, 2025). "Mutations such as BRAF V600E lead to the constitutive activation of MEK and ERK, driving uncontrolled tumor cell growth." (PMID 40861441, 2025). "BRAF upregulation correlates with PDGFC mutation, which promotes tumor growth, survival, angiogenesis, and metastasis." (PMID 41009348, 2025). "Mechanisms of RAI resistance include genetic mutations (e.g., BRAF V600E mutation, TERT promoter mutation), dysfunction of iodine-transporting proteins (e.g., NIS), and disturbances in the tumor microenvironment (TME)." (PMID 40530008, 2025). "This highlights the role of epigenetic reprogramming in enabling BRAF-mutated cells to exploit OIS escape pathways, promoting tumor formation and progression." (PMID 40872623, 2025). "The initial tumor was poorly differentiated adenocarcinoma, MLH1 and PMS2-deficient, and exhibited BRAF overexpression." (PMID 41170468, 2025).